CASP1 (caspase 1)
Diseases named in the same sentence as CASP1 in open-access papers (continued):
Sharing a sentence is not in itself a finding about the gene and the disease.
infection (continued). "Both PAO1ΔMotABCD and PAO1ΔMotABCD/ΔFliC showed similar neutrophil uptake after 45 minutes of infection, which allowed evaluating the direct importance of Flagellin in P. aeruginosa-driven Caspase-1-dependent neutrophil pyroptosis." (PMID 35849616, 2022). "Western blotting was used to detect caspase-1 expression in J774A.1 macrophage-like cells after infection with the SE strains." (PMID 36013975, 2022). "Inflammasomes are a molecular platform that are assembled to process pro-caspase 1 and subsequently promote secretion of interleukin (IL)-1β/IL-18 for proinflammatory responses induced upon infection." (PMID 35173184, 2022). "In canonical pathway, inflammasomes such as NLRP3, NLRP4 and AIM2 are responsible for recognizing extracellular pathogens infection and then activate the caspase-1, which cleaves GSDMD into the N-terminus and C-terminus fragments later." (PMID 35573789, 2022). "Infection with these clinical strains also led to caspase-1 activation in BMDMs and significant increases in IL-1β and IL-18 production." (PMID 35277504, 2022). "Both NAC and Ebselen significantly decreased the levels of caspase-1 activation during PA103 infection." (PMID 35202178, 2022). "The NLRP3 inflammasome, which contains the NOD-like receptor NLRP3, the adaptor ASC, and the effector caspase-1, is the most studied and best characterized inflammasome regarding infection and in chronic inflammatory diseases." (PMID 36145246, 2022). "By contrast, in 2019, it was reported that mice treated with a caspase-1 inhibitor displayed prolonged survival upon infection with rabies." (PMID 36298668, 2022). "Due to abortive infection, caspase-1 is activated by CD4+ T cells through interferon-inducible protein 16 (IFI16)." (PMID 36411423, 2022). "Despite its many similarities to S. Typhimurium, infection of THP-1 cells with S. Typhi triggers increased caspase-1 cleavage, IL-1β secretion and cell death – in contrast to infection with S. Typhimurium." (PMID 35801644, 2022). "We used B6.Nramp transgenic mice carrying a functional Nramp1 gene on a B6 background to evaluate the impact of Casp-1,11 during infection with ST." (PMID 34864057, 2022). "Our data lead us to propose a model whereby PMNs transmigrate into the inflamed intestine, Caspase-1 is activated and IL-1β released to trigger epithelial cell death and shedding of infected cells to protect the epithelium from ongoing infection." (PMID 36191054, 2022). "New research finds that mice lacking caspase-1 are more susceptible to Francisella compared to mice lacking IL-1β and IL-18, suggesting cell death itself and other caspase-1-dependent pathways help restrict infection." (PMID 36189207, 2022). "Using these models, they showed that inflammasome pathway components (NLRP3, ASC, AIM2, and caspase-1) are induced upon infection of bone marrow-derived macrophages." (PMID 36298668, 2022). "With the notable exception of Staphylococcus aureus, we observed that all bacteria triggered Caspase-1-dependent IL-1β release in our experimental setups, thus confirming Caspase-1 activation in neutrophils upon infection with various bacterial pathogens." (PMID 35849616, 2022). "Mice that received JWH133 treatment had significantly lower levels of NLRP3, ASC, and reduced caspase-1 activation at 24 h after PA infection." (PMID 36463179, 2022). "Pyroptosis has long been considered to be caspase-1-mediated death of monocytes following infection by certain bacteria." (PMID 35991122, 2022). "In contrast, infection of WT and Nlrc4-/- BMNs with P. aeruginosa strains of which neutrophil cell lysis is partially Caspase-1-dependent (PAO1 and CHA strains) also showed a partial involvement of NLRC4 in controlling neutrophil lysis." (PMID 35849616, 2022). "Even flagellated L. longbeachae was previously demonstrated to fail to trigger caspase-1 activation and pore-forming activity in mouse or human macrophages, only modest caspase-3 and cell apoptosis were observed at late stages of infection." (PMID 36677366, 2022).
infection (continued). "Caspase-1 activation was significantly increased in Nlrc4−/− BMDMs during infection with ΔfliCΔgalE and ΔfliCΔgalE::pBAD33 strains compared to ΔfliC, but no such differences were observed in Nlrp3−/− BMDMs infected with different mutant strains." (PMID 35630356, 2022). "It was shown that Ad5 infection of THP-1 macrophages resulted in increased secretion of cleaved caspase-1 and IL-1β." (PMID 36298668, 2022). "RT-qPCR showed that the mRNA levels of caspase-1/-4, Il-18 and Tnf-α were upregulated at 3 dpi, and continued to increase with ongoing infection." (PMID 35639503, 2022). "Viral genomes colocalized with IFI16 as early as 1 h post-infection and activation of caspase-1 was later detected (4 hpi)." (PMID 35458396, 2022). "Studies using Salmonella typhymurium infection of macrophages or cells stimulated with LPS and ATP, showed that caspase-7 activation was caspase-1-dependent." (PMID 36532444, 2022). "Diminished cleaved caspase-1 expression was even more prominent when the Western blotting was performed on samples from an infection performed at an MOI = 0.1, likely due to the fact that activation of caspases is dependent on the extent of virus replication." (PMID 35237259, 2022). "In contrast, we observed an increase of caspase-1 cleavage after wild type infection compared to mutant and rescue of wild type phenotype after B1940ΩhrpA/hrpA + complemented strain infection." (PMID 35765029, 2022). "Detection of caspase 1 revealed increased protein level in infected EVs post-infection at 48 and 72 h infection in a dose-dependent approach." (PMID 34926703, 2021). "Surprisingly, despite the significant reduction in cytotoxicity in Card19lxcn cells, processing of caspase-1 was equivalent in B6 and Card19lxcn cells 15 minutes post-infection, at which time cell death is virtually undetectable in either genotype." (PMID 34648590, 2021). "Hallmarks of cell death and inflammation, including cleaved caspase-1 and −3, gasdermin-D, neutrophil elastase, catalase, complement C3, and myeloperoxidase were validated in lung tissues on day 6 after infection via immunoblot." (PMID 34319784, 2021). "Several recent studies found that caspase and caspase 4 of F. merguiensis, caspase 2 of L. vannamei and caspase 1 of P. monodon were all up-regulated in the hemocytes after DIV1 infection." (PMID 34512588, 2021). "While Casp8/Ripk3/Casp1/11−/− BMDMs were protected from cell death in the early stage of infection with B. thailandensis, this delay in cell death resulted in increased formation of MNGCs via cell-cell fusion." (PMID 34154417, 2021). "(M–P) Gene expression analysis of Tnf (M), Casp1 (N), Il1b (O), and Il6 (P) in hypothalamus of young and old mice 8 days post-infection." (PMID 34151773, 2021). "The astrocytes were also pre-treated with VX765, a caspase-1 inhibitor, prior to infection and the cell viability after infection was assessed with MTT staining." (PMID 33796483, 2021). "When autophagy cannot eliminate an intracellular infection, caspase-1 is activated to initiate pyroptosis." (PMID 33644066, 2021). "In the process of infection with macrophages, the secreted SopA protein of Salmonella enterica locates in the mitochondria to activate the caspase-1 independent pathway via the TTSS and leads to macrophage death." (PMID 35097049, 2021). "F. novicida has served as a prototype for activation of the AIM2 inflammasome and it has been demonstrated that the infection leads to activation of caspase-1 and cleavage of the precursors of IL-1β and IL-18, thereby leading to their secretion." (PMID 35004352, 2021). "Caspase-1 activation usually leads to maturation and release of the proinflammatory interleukin 1β (IL-1β), which can recruit neutrophils and macrophages to sites of infection, we thus tested whether mutation of c3564/c3565 and hlyA influences IL-1β release during UPEC-induced pyroptosis." (PMID 34653218, 2021).
infection (continued). "The relative expression of NLRP3, ASC and caspase-1 mRNA was generally upregulated first and then downregulated in the infection groups." (PMID 33678162, 2021). "Infection with mCoV-A59 further enhanced caspase-1 cleavage (p20 active heterodimer) as well as expression of inflammasome components, Casp1 and Nlrp3, in old mice." (PMID 34151773, 2021). "In conclusion, we found that pathogenic E. coli HPI infection of Yunnan Saba pigs upregulated the expression of NLRP3, caspase-1, IL-1β and IL-18 mRNA, and promoted cell membrane pore formation and nuclear DNA damage in macrophages." (PMID 33678162, 2021). "Infection of wild-type BMDMs with ΔpknF mutant induced a significant production of IL-1β, whereas secretion of IL-1β was completely abrogated in Casp1-/- BMDMs while only partially impaired in Casp11-/- BMDMs." (PMID 34324582, 2021). "In SFTSV infected cells, accumulation of NLRP3, pro-caspase-1, and cleaved caspase-1 was observed compared with the mock infection, and ASC dimer, trimer, and oligomer were detected in the infected cells." (PMID 33708197, 2021). "Compared with the mock infection, pro-IL-1β in cell lysates, IL-1β and cleaved caspase-1 (p20) in supernatants were induced by LPS, LPS/Nigericin, and SFTSV." (PMID 33708197, 2021). "When an infection or intracellular danger signal appears, the inflammasome recruits and activates caspase-1 precursor directly or through ASC to form activated caspase-1." (PMID 34222479, 2021). "When an abortive infection of a cell occurs, due, for instance, to imperfect reverse transcription, the cell experiences pyroptosis driven by the caspase-1 pathway." (PMID 33542308, 2021). "Infection of Casp-1 inhibitor-treated cells and NOD-, LRR- and pyrin domain-containing 3 (NLRP3)-knockdown cells indicated that NLRP3 is essential for FMDV-induced IL-1β secretion." (PMID 35062226, 2021). "In our study, we observed that inhibition or knockdown of NLRP3 markedly blocked H2-induced Casp1 activation and mature IL-1β secretion and also had a significant effect on cell death, indicating that H2 infection activated the NLRP3 inflammasome pathway." (PMID 34009097, 2021). "During the initial stage of infection, the yeast predominantly drives pyroptotic cell death downstream of caspase-1." (PMID 33735255, 2021). "The positive cell rate of NLRP3 and caspase-1 in the three infection groups increased first and then decreased during the period from 0.5 to 9 h post-infection." (PMID 33678162, 2021). "In a more functional view, the NLRP7 inflammasome has been described as being involved in the activation of caspase-1 and IL1β release following infection of THP-1 cells (monocytes cell line) by Mycobacterium bovis." (PMID 34572309, 2021). "Consistent with mouse survival during infection, WT and Gsdmd−/− mice harbored less B. thailandensis, while Casp1/11−/− and Casp8/Ripk3/Casp1/11−/− mice harbored increased bacteria." (PMID 34154417, 2021). "We next determined the role of caspase-1 in cell death and IL-1β secretion during infection with early and chronic isolates of P. aeruginosa using a THP-1 cell line that is sevenfold deficient in caspase-1 (THP-1-defCASP1)." (PMID 33664232, 2021). "Expression of caspase-8 can also trigger the formation of ASC and activation of caspase-1 in case of pathogen infection." (PMID 34122107, 2021). "Candidalysin is both a central trigger for NLRP3 inflammasome-dependent caspase-1 activation via K+ efflux and a key driver of inflammasome-independent cytolysis of macrophages upon infection with C. albicans." (PMID 34795266, 2021). "The IL-1β is typically activated in macrophages after inflammasome sensing of infection or danger, leading to caspase-1 processing and driving inflammation after the release from macrophages." (PMID 34066479, 2021). "(J) Immunoblot analysis of caspase-1 cleavage showing higher inflammasome activation in VAT in aged mice post-infection." (PMID 34151773, 2021).
infection (continued). "In combination with the detection of caspase-1 level, we discovered that the infection with WT strain led to more severe intestinal inflammatory injury." (PMID 34804044, 2021). "The protein expression levels of activated caspase-1 (p20) and mature IL-1β (mIL-1β) in the infection group were significantly higher than those in the control group." (PMID 34603335, 2021). "Regarding the analysis of cell death markers by Western blot, we found activation of the pyroptosis marker caspase-1 in HL-1 cells, whereas active caspase-3, an apoptosis marker, was detected in HL-1 cells and HeLa cells post infection." (PMID 34578416, 2021). "Infection with B. thailandensis triggered caspase-1 mediated release of IL-1β and IL-18 and caspase-11 induced activation of the NLRP3 inflammasome leading to death of infected lung epithelial cells by pyroptosis in mice." (PMID 33329561, 2020). "Similar to our findings with TLR2 KO animals, caspase-1 also contributed to S. aureus containment during craniotomy infection but with distinct kinetics." (PMID 32290861, 2020). "Flow cytometric analysis using FAM-YVAD-FMK, a probe which preferentially detects active caspase-1, 4 and 5, showed an increase in caspase activation by neutrophils following infection with GAS." (PMID 33585270, 2020). "YopM inhibition of caspase-1 activity also inhibits the downstream effect of pyrin-mediated inflammasomes, exacerbating the infection." (PMID 32508813, 2020). "Compared to uninfected neutrophils, 5448 infection significantly increased pro-caspase-1 (50kDa) at 30 min, 60 min (p<0.05) and 180 min (p<0.01), whilst 5448AP infection only significantly increased pro-caspase-1 at 180 min (p<0.001)." (PMID 33585270, 2020). "Caspase-1/11-mediated pyroptosis stimulates immune responses that recruit neutrophils and phagocytes to the site of infection and help eradicate pathogens." (PMID 32295272, 2020). "In the later stages of infection, caspase-1, and inflammasome would become more important for the production of mature IL-1β." (PMID 33644037, 2020). "The increased tissue pathology of TLR2 KO versus caspase-1 KO animals agrees with the finding that S. aureus burden was increased early post-infection and more dramatically in TLR2 KO mice." (PMID 32290861, 2020). "Specifically, heightened bacterial burdens were primarily evident at day 14 post-infection in the galea and brain of caspase-1 KO animals, whereas TLR2 was critical during acute infection (i.e., day 3) and beyond." (PMID 32290861, 2020). "The inflammasome controls infection through activation of caspase-1 leading to either IL-1β dependent inflammation, or pyroptotic cell death in infected cells." (PMID 32013758, 2020). "Taken together, our results show that Casp1/11 and Asc are required for IL-1β processing following infection with M. tuberculosis clinical isolates." (PMID 32111888, 2020). "Since IL-1β expression was significantly reduced in the brain of TLR2 KO mice as well as TLR2-deficient microglia and macrophages, we next examined the functional importance of caspase-1 during S. aureus craniotomy infection using caspase-1 KO mice." (PMID 32290861, 2020). "Western blot analysis showed the activated caspase 1 (~20 kDa) at 24 h post-infection, and a more prominent band was observed at 48 h post-infection with DENV-2." (PMID 32210961, 2020). "This indicated that caspase-1 activation and cytokine maturation are uncoupled from cell death during infection with clinical isolates of M. tuberculosis." (PMID 32111888, 2020). "Significant increments in parasite burden of Casp-1/11−/− mice were also observed in liver (3 days of infection) and brain (30 days of infection) samples." (PMID 32523898, 2020). "Collectively, these findings demonstrate the functional importance of caspase-1 in bacterial containment during S. aureus craniotomy infection with a NLR sensor that remains to be identified." (PMID 32290861, 2020).
infection (continued). "The relationship between TLR2 and caspase-1 is also supported by the disparate kinetics of each KO mouse during infection." (PMID 32290861, 2020). "We also established a role for IL-1β during craniotomy infection by the ability of exogenous IL-1β delivery to prevent heightened bacterial burden in caspase-1 KO mice." (PMID 32290861, 2020). "At the beginning of a S. Typhimurium infection in vivo, baseline tissue expression of Casp11 is low but is upregulated over the course of infection, whereas Casp1 transcript levels are high at baseline and decline slightly as the infection progresses." (PMID 32282854, 2020). "Infection with the wild-type (WT) Shigella flexneri strain 2457T but not the avirulent BS103 strain (which lacks the virulence plasmid) resulted in CASP1-dependent cell death in both mouse and human cells." (PMID 33074100, 2020). "The results indicated a sharp ROS production in WT macrophages especially during at 3 h of infection, while a marked decreased of the relative fluorescence was perceived in Casp-1/11−/− infected BMDMs in both time of 3 and 18 h after infection." (PMID 32523898, 2020). "THP1 monocytes were treated with caspase-1 inhibitor VX-765 (10 μM) 15 min before LPS treatment or infection with H. pylori, which followed Nigericin-mediated NLRP3 inflammasome activation." (PMID 32230726, 2020). "In contrast, bacterial burden was most affected in caspase-1 KO mice at day 14 post-infection, in agreement with caspase-1 activity occurring subsequent to TLR2 signaling to maximize IL-1β production." (PMID 32290861, 2020). "Consistent with this, inflammasome in response to T. gondii requires Nrlp1b-mediated Casp1 activation during late infection." (PMID 33193165, 2020). "Complementation of VPRH restored all of the inflammasome-mediated phenotypes upon BMDM infection, including rapid cell death, IL-1β secretion, as well as cleavage of caspase-1, maturation of IL-1β, and cleavage of GSDMD." (PMID 32013758, 2020). "Multiple studies show that IL-1β is typically activated in macrophages after inflammasome sensing of infection or danger, leading to caspase-1 processing of IL-1β and its release." (PMID 33391283, 2020). "Wild type (WT), TLR2 knockout (KO), TLR9 KO, and caspase-1 KO mice were examined at various intervals post-infection to quantify bacterial burden, leukocyte recruitment, and inflammatory mediator production in the galea, brain, and bone flap." (PMID 32290861, 2020). "After infection of T. gondii, mGbp2B (also named Gbp1) can activate inflammasome complex signaling cascades, which leads to Nlrp1, Nlrp3, Nlrp4, and pro-caspase-1 degradation resulting in converting the cell death type from pyroptosis to apoptosis." (PMID 32731337, 2020). "ASC specs were found in the plasma of HIV positive patients, and infection with HIV stimulated the NLRP3 inflammasome in monocytes as well as production of caspase-1, IL-1β and IL-18 in brain microglial cells." (PMID 32066471, 2020). "NLRP3 inflammasome is assembled by NLRP3, ASC, and Caspase-1 after exogenous infection and endogenous signal stimulation; subsequently, there is Caspase-1 activation and the release of downstream inflammatory factors, such as IL-1β and IL-18." (PMID 32195267, 2020). "Expression profiles of Casp1 and Casp11 in the cecal tissues of WT mice revealed that Casp11 transcripts increased over the course of infection, while Casp1 levels decreased, which is consistent with other reports." (PMID 32282854, 2020). "Our findings identified a critical role for both TLR2 and caspase-1 in preventing bacterial outgrowth in the brain, galea, and bone flap during S. aureus craniotomy infection, suggestive of pathway cooperativity." (PMID 32290861, 2020). "Of the three caspase genes, caspase-1 was upregulated at day 2 compared to day 5 and caspase-2 was upregulated at day 3 compared to day 7 infection, however, in both cases the changes in gene expression were relatively minor." (PMID 33424791, 2020).